ATG13 (autophagy related 13)
Description:
Autophagy factor required for autophagosome formation and mitophagy. Target of the TOR kinase signaling pathway that regulates autophagy through the control of the phosphorylation status of ATG13 and ULK1, and the regulation of the ATG13-ULK1-RB1CC1 complex. Through its regulation of ULK1 activity, plays a role in the regulation of the kinase activity of mTORC1 and cell proliferation.
Synonyms: KIAA0652; PARATARG8
Tractability: Small molecule: a structure with a bound ligand is known. Antibody: the Human Protein Atlas places it where antibodies can reach. PROTAC: ubiquitination databases record sites on it; its protein half-life has been measured.
Gene: Protein-coding gene on chromosome 11 (46,617,251 to 46,674,818, forward strand). Ensembl gene ENSG00000175224.
Subcellular location: Cytoplasm, cytosol; Preautophagosomal structure
Subcellular location (Human Protein Atlas): Cytosol; Nucleoplasm; Plasma membrane
Pathways (Reactome):
Autophagy: Macroautophagy
Gene Ontology:
Molecular function: kinase activator activity; protein binding; protein kinase binding; protein kinase regulator activity
Biological process: autophagosome assembly; negative regulation of cell population proliferation; positive regulation of autophagy; positive regulation of establishment of protein localization to mitochondrion; regulation of protein lipidation; macroautophagy; mitophagy; piecemeal microautophagy of the nucleus; protein localization to phagophore assembly site; autophagy; regulation of cell population proliferation; response to mitochondrial depolarisation
Cellular component: Atg1/ULK1 kinase complex; cytosol; mitochondrion; phagophore assembly site; phagophore assembly site membrane; phosphatidylinositol 3-kinase complex, class III; cytoplasm; endoplasmic reticulum membrane
Genetic constraint (gnomAD): Loss-of-function variants: 20 observed, 61.41 expected, observed/expected ratio (o/e) 0.33, 90% interval 0.23 to 0.47. The upper end of that interval is the gene's LOEUF score, 0.47, which puts it in group 2 of 6, group 1 being the genes least tolerant of losing a copy. Missense variants: 561 observed, 706.66 expected, observed/expected ratio (o/e) 0.79, 90% interval 0.74 to 0.85. Synonymous variants: 251 observed, 258.3 expected, observed/expected ratio (o/e) 0.97, 90% interval 0.88 to 1.08.
Homologues: Orthologues: chimpanzee ATG13 (99% identical), macaque ATG13 (99% identical), dog ATG13 (98% identical), pig ATG13 (98% identical), rabbit ATG13 (97% identical), rat Atg13 (95% identical), guinea pig ATG13 (95% identical), mouse Atg13 (82% identical), tropical clawed frog atg13 (72% identical), zebrafish atg13 (69% identical), Drosophila melanogaster Atg13 (30% identical), Caenorhabditis elegans atg-13 (21% identical).
Diseases named in the same sentence as ATG13 in open-access papers:
ATG13 is named in the same sentence as 68 diseases in open-access papers, as found by Europe PMC text mining. Sharing a sentence is not in itself a finding about the gene and the disease. The quoted sentences say what the papers report.
ovarian carcinoma (9 papers, 2017 to 2026). A malignant neoplasm originating from the surface ovarian epithelium. "For instance, circMUC16 was proven to directly bind with ATG13 to promote autophagy in ovarian cancer." (PMID 36187468, 2022). "Autophagy-related protein 13 (ATG13) phosphorylation is a crucial bioprocess in autophagy in epithelial ovarian cancer (EOC)." (PMID 33996533, 2021). "Our findings demonstrated that ING5 up-regulated LC-3B, Beclin 1 and ATG13 expression with autophagy strengthened in ovarian cancer cells, indicating that ING5 induced autophagy in Beclin 1-dependent manner." (PMID 29262575, 2017). "For example, circMUC16 is highly expressed in ovarian cancer tissues and can bind to ATG13 protein." (PMID 34445958, 2021). "Therefore, circMUC16 first promotes autophagy of ovarian cancer through Beclin1, Runx1 and ATG13, and then the progression of ovarian cancer." (PMID 34445958, 2021). "In addition, circMUC16 can directly associate with ATG13, stabilize its expression, and then promote autophagy in epithelial ovarian cancer by regulating Beclin1, RUNX1, and ATG13." (PMID 38338839, 2024). "Conclusion: 1) MiR-8485 may be the key factor of BJOE in promoting autophagy and apoptosis and inhibiting cell proliferation of ovarian cancer cells; 2) BJOE may play an antitumor role by regulating LAMTOR3/mTOR/ATG13 signaling axis through miR-8485 to promote autophagy in ovarian cancer cells." (PMID 35959437, 2022).
atherosclerosis (5 papers, 2017 to 2025). A disease characterized by the build-up of fatty material and calcium deposition in the arterial wall resulting in partial or complete occlusion of the arterial lumen. "Furthermore, they have been reported to promote autophagy by inducing demethylation of the Atg13 promoter region, thereby attenuating atherosclerosis." (PMID 40699727, 2025). "Additionally, they may attenuate atherosclerosis by promoting autophagy through epigenetic mechanisms involving DNA and Atg13 promoter demethylation." (PMID 40699727, 2025). "The expression of autophagy markers ATG13 and LC3 in aortic intimal ECs with severe atherosclerosis was found to be significantly higher than the expression in those without atherosclerosis." (PMID 35096837, 2021). "In summary, this study demonstrated that moderate autophagy induced by low-dose rapamycin could alleviate atherosclerosis progression and promote plaque stability in the ApoE−/− mice model, which was associated with regulating VSMC autophagy and senescence by the mTORC1/ULK1/ATG13 signal pathway." (PMID 28713484, 2017). "The signals of LC3 and ATG13 were low in intimal CD31-positive ECs in patient without significant atherosclerosis; while the p-S6K signal was found." (PMID 28607460, 2017). "In human atherosclerosis specimens, expression of autophagy markers, ATG13 and LC3, were more abundant in aortic intimal ECs with severe atherosclerosis than those without atherosclerosis." (PMID 28607460, 2017).
cervical carcinoma (4 papers, 2019 to 2024). A carcinoma arising from either the exocervical squamous epithelium or the endocervical glandular epithelium. "In summary, our study demonstrated that CD40 activation is associated with ATG13 expression and autophagy by increasing the phosphorylation level of ERK in cervical carcinoma cells." (PMID 39696986, 2024). "RAME treatment increased the mRNA levels of ATG genes (ULK1, ATG5, BECN1, ATG7, ATG12, and ATG13) dose dependently in cervical cancer cells." (PMID 31387554, 2019). "In this study, we used cervical carcinoma cells and demonstrated that CD40 ligation enhanced the formation of autophagosomes, consequently promoting autophagic flux by increasing ATG13 expression." (PMID 39696986, 2024).
colon cancer (3 papers, 2021 to 2024). "Whereas it was lowly expressed in colon cancer patients compared with polyp patients, which led to the inhibition of ATG13 by binding miR-361." (PMID 36313671, 2022). "In addition, circHADHA improved autophagy regulated by miR-361 and ATG13 in both colon epithelial and cancer cells, and circHADHA-augmented autophagy impeded cell proliferation in colon cancer cells and colon cancer cell-derived xenograft tumors." (PMID 36313671, 2022). "Moreover, circHADHA-augmented autophagy impeded cell proliferation mediated by miR-361/ATG13 in colon cancer cells." (PMID 36313671, 2022). "ATG13 knockdown reduced autophagy even in the presence of circHADHA in colon cancer cells." (PMID 36313671, 2022). "Treatment of HCT116 ATG16L1 T300 colon cancer cells with AR12 or neratinib increased the activities of the AMPK, ULK1 and ATG13." (PMID 34252884, 2021). "Additionally, for LoVo colon cancer cells, irinotecan inhibits mTOR and activates the autophagy-related genes, ULK1, ATG13, ATG4L, and AMBRA1, promoting autophagy with increased numbers of lysosomes and lysosomal activity, which contribute to irinotecan resistance." (PMID 39456585, 2024). "Furthermore, we performed autophagy assay in colon cancer cells with present or absent circHADHA and showed that circHADHA regulated autophagy via the miR-361/ATG13 axis." (PMID 36313671, 2022).
glioblastoma (3 papers, 2020 to 2023). The most malignant astrocytic tumor (WHO grade IV). "In the KRAS-driven glioblastoma mouse model, autophagy blocked Atg7, Atg13, or Ulk1 by shRNA; inhibited the occurrence and growth of tumors; and extended the survival of mice." (PMID 33194668, 2020). "Similarly, deletion of Atg13 or Ulk1 in a KrasG12D-driven glioblastoma decreases tumor progression." (PMID 32308763, 2020).
lung carcinoma (3 papers, 2016 to 2017). "Here, it was found that ING5 overexpression in vivo and vitro induced the autophagy of lung cancer cells with ATG13, ATG14 and Beclin-1 overexpression, indicating that ING5-induced autophagy was dependent on Beclin-1 and belonged to canonical pathway." (PMID 27409347, 2016). "Combined, but not individual, treatment of lung cancer cells strongly increased the phosphorylation of eIF2α S51, ATG13 S318, JNK and p38 whereas it decreased the phosphorylation of AKT T308, p70 S6K T389, mTOR S2448 and ULK-1 S757." (PMID 27903966, 2017).
myocardial infarction (3 papers, 2020 to 2023). Gross necrosis of the myocardium, as a result of interruption of the blood supply to the area, as in coronary thrombosis. "Besides, researchers also observed that after acute myocardial infarction (AMI), the activity of miR-1 and miR-206 can be increased by histamine, leading to a decrease in autophagy activation and cell apoptosis under hypoxia and AMI conditions by acting on Atg13." (PMID 32148656, 2020).
breast carcinoma (2 papers, 2023 to 2025). "Erα inhibitor oxabicycloheptene sulfonate could reduce the expression of ATG13, leading to restrain the viability of breast cancer cells." (PMID 37700273, 2023). "ULK1 could active autophagy via phosphorylating ATG13 to inhibit the progress of breast cancer." (PMID 37700273, 2023).
colorectal cancer (2 papers, 2021 to 2023). A primary or metastatic malignant neoplasm that affects the colon or rectum. "As expected, the level of HIF-1α, Lon, ULK1, and ULK1 downstream autophagy proteins, ULK1-S555 phosphorylation, ATG13, and FIP200, was increased under hypoxia exposure or CoCl2 treatment in HCT-15 colorectal cancer cells and in FADU, HSC-3 and OEC-M1 oral cancer cells." (PMID 36927870, 2023).
hepatocellular carcinoma (2 papers, 2023 to 2025). A malignant tumor that arises from hepatocytes. "LicoA activated the ULK1/Atg13 complex to induce autophagy and apoptosis via the generation of ROS in human hepatocellular carcinoma cells." (PMID 40002335, 2025).
renal cell carcinoma (2 papers, 2020 to 2025). "On the other hand, in renal cell carcinoma (RCC), it regulates autophagy via the PI3K/AKT/Atg13 pathway, a process less commonly reported in other cancers." (PMID 40616679, 2025).
Sepsis (2 papers, 2023). Sepsis is defined as life-threatening organ dysfunction caused by a dysregulated host response to infection. "This suggested that Atg13 played an important role in HYP-mediated protection against sepsis-induced ALI by activating autophagy." (PMID 37545738, 2023). "In summary, we suggested that HYP attenuated sepsis-induced ALI via regulating Atg13-mediated autophagy and inhibiting inflammation." (PMID 37545738, 2023). "Inhibiting autophagy or silencing Atg13 reversed the protective effect of HYP against sepsis-induced ALI." (PMID 37545738, 2023). "Proteomics detection showed that Atg13 played a vital role in HYP-mediated protection against sepsis-induced ALI." (PMID 37545738, 2023). "This suggested that Atg13 played an important role in HYP-mediated protection over sepsis-induced ALI by activating autophagy." (PMID 37545738, 2023). "This research indicated the treatment efficacy of HYP and the mechanism in sepsis-induced ALI via Atg13-mediated autophagy." (PMID 37545738, 2023). "It is very important to explore the role of LILAR in modulating Atg13 expression in sepsis." (PMID 37829506, 2023). "The proteomic analysis showed that HYP treatment resulted in the abnormal expression of proteins in lung tissues in mice with sepsis-induced ALI, including Atg13 expression in the HYP treatment group." (PMID 37545738, 2023). "3-MA treatment had a similar effect as Atg13 silencing, which reversed the protective effects of HYP against sepsis-induced ALI." (PMID 37545738, 2023).
acute myeloid leukemia (1 paper, 2023). Acute myeloid leukemia (AML) is a group of neoplasms arising from precursor cells committed to the myeloid cell-line differentiation. "Autophagy-related proteins such as ULK1, ATG3, ATG5, ATG13, and ATG14 were markedly expressed in various acute myeloid leukemias when comparing the microarray-based expression profiling of distinct ATG proteins from human AML samples with the human normal hematopoiesis." (PMID 37180758, 2023).
Alzheimer disease (1 paper, 2023). A progressive, neurodegenerative disease characterized by loss of function and death of nerve cells in several areas of the brain leading to loss of cognitive function such as memory and language. "Lnc_Atg13 was an important component of the mTOR pathway, which contributes to the synthesis of synaptic proteins and is strongly linked to the pathophysiology of Alzheimer’s disease." (PMID 37106826, 2023).
chronic fatigue syndrome (1 paper, 2025). "The inflammatory and chronic demyelinating pathologies due to atg13 ablation could be relevant to the pathogenesis of Myalgic encephalomyelitis or chronic fatigue syndrome (ME/CFS) and therefore may shed light in the molecular mechanism in post-exertional malaise (PEM)." (PMID 40799759, 2025).
colon adenocarcinoma (1 paper, 2024). "We analyzed the correlation between KRAS mutational status and expression of several autophagy genes, including MAP1LC3B, ATG5, ATG10, ATG13, and ATG14 in both COAD (colon adenocarcinoma) READ (rectum adenocarcinoma) as well as normal tissue." (PMID 39057088, 2024).
coronary atherosclerosis (1 paper, 2017). Atherosclerosis of the coronary vasculature. "But in patient with severe coronary atherosclerosis, double immunofluorescent staining revealed that LC3 and ATG13 were highly expressed in aortic intimal ECs and no p-S6K signal can be found." (PMID 28607460, 2017). "In human aortic specimens, we investigated the expression of autophagy-related proteins, LC3 and ATG13 in aortic ECs in patients with or without severe coronary atherosclerosis." (PMID 28607460, 2017).
coronary heart disease (1 paper, 2024). "We identified eight hub genes (CIRBP, USP7, ELAVL1, ATG13, ALOXE3, PRKAA2, USP11, SLC38A1) that exhibited significant differences between coronary heart disease (CAD) patients and healthy controls." (PMID 39610972, 2024).
diabetes (1 paper, 2019). "Our findings on the association between genetic variants in AMBRA1, ATG13 and ATG16L1 and proinsulin levels are in agreement with previous evidence reporting autophagy deficiency as an important determinant in the pathogenesis of insulin resistance and diabetes." (PMID 30908504, 2019).
Headache (1 paper, 2023). Cephalgia, or pain sensed in various parts of the head, not confined to the area of distribution of any nerve. "Additionally, among the overlapping genes between migraine and headache with glycemic traits, five genes have previously been associated with migraine (THADA, EHMT2, AMBRA1, and SMG6) and headache (ATG13); now, these genes are also implicated in glycemic traits." (PMID 36808568, 2023).
immunoglobulin A deficiency (1 paper, 2020). "Also related with the immune system is an ATG13 variant that may be associated with selective immunoglobulin A deficiency (IgAD), although it is not clear if this polymorphism affects ATG13 or AMBRA1 (which is another gene involved in autophagy)." (PMID 33147747, 2020).
iron deficiency (1 paper, 2025). "We assessed whether the core autophagy proteins Atg5, Atg8, Atg11 and Atg13 are involved in mitochondrial degradation upon iron deficiency." (PMID 40716740, 2025).
leukemia (1 paper, 2020). A malignant (clonal) hematologic disorder, involving hematopoietic stem cells and characterized by the presence of primitive or atypical myeloid or lymphoid cells in the bone marrow and the blood. "Atg13 and FIP200 are reduced in TRPM2-depleted leukemia cells, and this may contribute to reduced ULK1 stability." (PMID 32312983, 2020).
melanoma (1 paper, 2019). A malignant, usually aggressive tumor composed of atypical, neoplastic melanocytes. "Among them, we found several autophagy-related genes such as AMBRA1, ATG5, ATG12, ATG13 and ATG4B, which could be potentially downregulated in BRAFi-resistant melanoma cells." (PMID 30254376, 2019).
mesothelioma (1 paper, 2015). A usually malignant and aggressive neoplasm of the mesothelium which is often associated with exposure to asbestos. "In this study, we have shown for the first time that GDC-0980 is active in a subset of mesotheliomas, which can be identified by the presence of ATG13 puncta." (PMID 26284517, 2015). "In summary, we show that GDC-0980 is effective in mesothelioma 3D models that display ATG13 puncta, and that blockade of autophagy increases their response to chemotherapy." (PMID 26284517, 2015). "We have found that the presence of ATG13 puncta appear to identify these tumors, at least in mesothelioma." (PMID 26284517, 2015). "For the first time, we show a role for autophagy in the response to chemotherapy of 3D models of mesothelioma and propose ATG13 as a potential biomarker of the therapeutic responsiveness of mesothelioma." (PMID 26284517, 2015). "Again, we found that mesothelioma cells with ATG13 puncta were commonly seen in the spheroids of the sensitive group and rarely seen in the spheroids from the resistant group." (PMID 26284517, 2015). "By studying 3D models of mesothelioma, we have found that, whereas all spheroids demonstrated basal autophagy, only the sensitive spheroids displayed ATG13 puncta at baseline, increased autophagy in response to GDC-0980 and became more chemoresponsive with inhibition of autophagy." (PMID 26284517, 2015). "Hence, autophagy represents a possible therapeutic target in a subset of mesotheliomas and we propose the presence of ATG13 puncta as a promising autophagy marker to identify these tumors." (PMID 26284517, 2015). "Thus, autophagy, as measured by the presence of ATG13 puncta, correlated with the responsiveness to GDC-0980 in both 3D models of mesothelioma." (PMID 26284517, 2015).
migraine (1 paper, 2023). "Additionally, we note that many significant genes (e.g., AMBRA1, ATG13, ARHGAP1, CKAP5, LRP4, and DDB2) have been associated with migraine, headache, and proinsulin." (PMID 36808568, 2023).
non-small cell lung carcinoma (1 paper, 2024). A group of at least three distinct histological types of lung cancer, including non-small cell squamous cell carcinoma, adenocarcinoma, and large cell carcinoma. "To elucidate the impact of autophagic degradation, we used the non-small cell lung cancer (NSCLC) line U1810 (wt) and U1810 cells with a deficiency of ATG13 (koATG13), which are incapable of autophagy." (PMID 39543123, 2024).
nutritional deficiency (1 paper, 2022). "However, TRAF1-SINAT6-ATG13 TRAFasome promotes the stability of ATG13, which induces the biogenesis of autophagy in response to nutritional deficiency." (PMID 35806307, 2022).
prostate carcinoma (1 paper, 2025). A carcinoma that arises from epithelial cells of the prostate gland. "By influencing the splicing of genes such as ATG13 and SYTL2, PD‐L1 may alter the functional output of these proteins, which could ultimately contribute to the development and progression of castration‐resistant prostate cancer." (PMID 40923331, 2025).